MIR518F (microRNA 518f)
Synonyms: hsa-mir-518f; MIRN518F
Gene: MicroRNA gene on chromosome 19 (53,700,015 to 53,700,101, forward strand). Ensembl gene ENSG00000207706.
Gene Ontology:
Biological process: miRNA-mediated post-transcriptional gene silencing
Homologues: Orthologues: chimpanzee ptr-mir-518f (100% identical), macaque mml-mir-518f (92% identical). Paralogues in human: MIR523 (91% identical), MIR518C (90% identical), MIR518E (90% identical), MIR519C (89% identical), MIR526A1 (89% identical), MIR518D (87% identical), MIR516A1 (86% identical), MIR516B1 (86% identical), MIR520C (86% identical), MIR522 (86% identical), MIR524 (86% identical), MIR516A2 (85% identical), and 12 more.